IDO1 (indoleamine 2,3-dioxygenase 1)
Diseases named in the same sentence as IDO1 in open-access papers (continued):
Sharing a sentence is not in itself a finding about the gene and the disease.
tumor (continued). "It has been reported that the transcriptional factors p-NF-κB and/or p-STAT1 can be activated by IFN-γ and promote IRF1 expression, which promotes IDO1 expression in IFN-γ-treated human tumor cells." (PMID 38540186, 2024). "It is worth noting that induction of IDO1 expression in response to interferon-gamma (IFNγ), an effector molecule of CTLs in the tumor, is recognized as one of the tumor’s mechanisms of evading immune surveillance." (PMID 39346737, 2024). "In the tumor microenvironment, IDO1 is expressed by antigen-presenting cells such as macrophages, dendritic cells and tumor cells." (PMID 38254043, 2024). "Studies have shown that IDO1 fosters tumor cell neovascularization by elevating IL-6 levels, counteracting the anti-cancer effects of the inflammatory cytokine IFN-γ, thereby promoting cancer progression." (PMID 38883986, 2024). "The results revealed that, compared with the control group, the IDO1 inhibitor suppressed tumor formation, metastasis and angiogenesis." (PMID 38468343, 2024). "In general, although IDO1 inhibition can be improved by the combination of drugs, there are still many limitations in the use of IDO1 inhibitors, so it is necessary to explore new methods of IDO1 inhibition to lift tumor immunosuppression." (PMID 39253578, 2024). "Intriguingly, expression of the high-affinity Trp transport system in mouse and human tumor cells is induced by IDO1." (PMID 38813870, 2024). "IDO-1 expression occurs in the placenta, mucosa of the gut, certain tumours, tumour-draining lymph nodes, and immune cells." (PMID 38802702, 2024). "The upregulation of CD274, IDO1, etc. on the tumor surface by T cell activation and IFN-α/IFN-γ stimulation has been demonstrated." (PMID 38629071, 2024). "Next, quantitative PCR was performed to evaluate the expression of the pro-tumour TAM-associated genes IL-10, CCL2 and IDO-1, which were all increased in both SKOV-3 and OVCA433 generated TAMs compared to pre-cultured autologous monocytes." (PMID 39763667, 2024). "Areas annotated as having diffuse immune infiltration showed higher levels of MHCI (beta-2-microglobulin, B2M) and checkpoints IDO1, PD-L1, PD-1 and Tim-3 in tumor AOIs, and higher levels of T-cells (CD3) and Granzyme B in immune AOIs." (PMID 39026018, 2024). "Across different tumor types, expression of IDO1 is inversely correlated with infiltrating CD3+ and CD8+ T cells as well as NK cells, while being positively correlated with regulatory T-cell frequency." (PMID 39211039, 2024). "Despite the prominent role of the paralog IDO1 in immune cells (besides cancer and tumor microenvironment cells), little is known about the expression and the role of IDO2 in the human immune system." (PMID 39594642, 2024). "In contrast to both IDO1 and TDO, gene expression of IDO2 is limited in human tumor tissues, and tryptophan-metabolizing activity fully resides with co-present IDO1 in IDO2-expressing tumors." (PMID 39211039, 2024). "Compared with tumor grafts (TMM1, TMM7, or TMM9), TMM6 showed faster tumor growth, evident IDO1 expression, a lower relative Trp concentration, higher relative [Kyn]/[Trp] ratio, as well as a lower CD8+T proportion." (PMID 38540186, 2024). "Hanihara and colleagues reported a slight increase in the survival duration of mice given orthotopic intracranial GL261 cell tumours when they administered TMZ in combination with the weak IDO1 inhibitor 1-methyltryptophan (1-MT), compared to TMZ alone." (PMID 39048947, 2024). "Increased IDO1 and TDO2 activity is known to suppress the cytotoxic T cell response to tumour cells, and this has led to the proposal that the IDO1 and TDO2 enzymes represent promising immuno-oncology targets." (PMID 39048947, 2024). "The Kynurenine (Kyn) pathway is activated by the enzyme indoleamine 2,3-dioxygenase 1 (IDO-1) and has been shown to have a role in tumour progression." (PMID 38188364, 2024).
tumor (continued). "The GB microenvironment, particularly through the release of IL-6 and the expression of PD-L1 and IDO-1, is able to promote the formation of regulatory T cells (Tregs) that blunt the anti-tumor T cell response." (PMID 38730589, 2024). "As a potent immunostimulant, EPA nanovesicles reverse tumor immunosuppression by enhancing IDO1 inhibition, resulting in better anti-tumor cytotoxic T lymphocyte effects." (PMID 39766335, 2024). "Since discovery of the immunosuppressive role of IDO1 in tumor development, a great number of IDO1 inhibitors has been developed." (PMID 39211039, 2024). "In the tumor microenvironment, IDO1 is expressed by antigen-presenting cells such as macrophages, dendritic cells and tumor cells, and studies have shown that IFN-γ can induce IDO1 expression in macrophages at the transcriptional level." (PMID 38254043, 2024). "To look into the biological relevance of IDO1 expression in various tumor tissues, we analyzed the role of IDO1 in various tumors by GO functional annotation and KEGG pathway." (PMID 38539263, 2024). "The upregulated genes in PTCL‐TBX21 included Th1‐related genes, including CXCR3, CD38, INFG, CXCL9, CXCL11, IL27, and genes associated with tumor immunity, such as CD274 (PD‐L1), LAG3, and IDO1." (PMID 38234210, 2024). "In HCC, combining rosmarinic acid with IDO1-shRNA demonstrates inhibitory effects on tumor progression in vivo." (PMID 38462620, 2024). "Along with oxaliplatin, aNLG919, a derivatized IDO1 inhibitor, was encapsulated (IDO1 is an immunosuppressive protein often overexpressed in tumours)." (PMID 39273286, 2024). "Conversely, IDO1 promotes internal tumour neovascularization, further fostering tumour growth and survival." (PMID 38339367, 2024). "Similar to human tumors, IDO1 immunopositive cell populations included tumor cells, mononuclear immune cells, and stromal cells." (PMID 39061522, 2024). "IDO1, the expression of which is induced by interferon gamma, has been shown to have immunosuppressive effects, including countering the anti-tumor effects of immune checkpoint inhibitors." (PMID 39054485, 2024). "In HCC, IDO1 is responsible for T‐cell suppression and for tumour cells evading surveillance and clearance by the immune system." (PMID 38935536, 2024). "Based on in vivo models, tumor cell-expressed IDO1 thus appears to considerably contribute to the promotion of tumor growth, whereas a role for host IDO1 remains to be further substantiated." (PMID 39211039, 2024). "When targeted with folic acid, the uptake efficiency of Dox-IND/CPT nanovesicles in tumors was improved, the IDO1 pathway was significantly inhibited, and the tumor suppression effect was enhanced." (PMID 39766335, 2024). "In this boundary region, tumor cells activated IDO1 (cluster 6; log2 fold change = 0.86, adjusted p-value = 2.0e-65)." (PMID 39639005, 2024). "Since both hot tumors of this study showed IDO1 immunostaining in higher numbers of tumor cells, i.e., 40% and 60% of tumor cells, an additional inflammation mediated IDO1 upregulation should be considered." (PMID 39061522, 2024). "Extensive evidence supports the notion that tryptophan catabolism mediated by the IDO1 enzyme is the unique immune regulatory mechanism that promotes tumor growth." (PMID 38333210, 2024). "Kynurenine, a metabolite of tryptophan through IDO1, induces PD-1 on tumor-infiltrating CD8+ T cells." (PMID 38632994, 2024). "In conjunction with IDO1 expression on the tumor cell side, CCL22-positive cells create local environments that protect tumor cells from immune cell attacks." (PMID 39639005, 2024). "Specifically, our data show that combining IDO1/TDO2 inhibition with chemotherapy extends the overall survival of tumor-bearing mice beyond either therapy alone, highlighting a potential clinical approach to lengthening disease-free intervals." (PMID 38451784, 2024).
tumor (continued). "Tumors with a lack of calponin expression (n = 5; 5%) showed a wide range of IDO1 immunostaining in tumor cells, i.e., these neoplasms contained 1, 5, 15, 80, and 100% of IDO1-positive tumor cells, respectively." (PMID 39061522, 2024). "Analysis of IDO1 DNA methylation in UALCAN showed a significant (p < 0.0001) decrease in promoter methylation in HNSCC tumor samples (n = 528) compared to the adjacent normal tissues (n = 50)." (PMID 38736462, 2024). "Gene expression analysis using TIMER2.0 revealed significantly higher (p < 0.001) IDO1 expression in HNSCC tumor samples (n = 520) than in the adjacent normal tissues (n = 44)." (PMID 38736462, 2024). "IDO1, which is induced by interferon, can also suppress inflammatory responses targeting tumor cells." (PMID 39054462, 2024). "The immunosuppressive phenotype brought on by necrotic and apoptotic cells was also inhibited and tumor metastasis was prevented when cytarabine and IDO1 expression were inhibited together." (PMID 38655133, 2024). "Much attention has been paid to the potential roles of IDO1 in tumor immunobiology since the discovery that IDO1 modulates maternal–fetal tolerance." (PMID 39371092, 2024). "In neoplastic cells, the expression of IDO1 is induced by an inflamed tumor microenvironment or exists as a constitutive intrinsic feature." (PMID 39061522, 2024). "Collectively, the extensive prognostic, preclinical and early-phase clinical evidence linking deranged tryptophan metabolism to immunosuppression and tumor growth once positioned IDO1 inhibitors at the forefront of experimental immunotherapy." (PMID 39211039, 2024). "For example, it has been demonstrated that up-regulated levels of IDO1 in immunogenic mouse tumor cells block their rejection in preimmunized mice." (PMID 38813870, 2024). "IDO1-positive carcinomas (n = 90): Maximal stromal TILs at the invasive margin ranged from 1 to 70% and from 1 to 80% in the central tumor area." (PMID 39061522, 2024). "Epacadostat (formerly INCB024360) represents a novel, potent, and selective inhibitor of IDO1 in human tumor and dendritic cells." (PMID 39054430, 2024). "Various IDO1 inhibitors have been found to improve IDO1-mediated immunosuppression of tumor cells by inhibiting the IDO1 pathway, including NTRC 3883-0 and epacadostat (INCB024360, EPA)." (PMID 39253578, 2024). "In preclinical studies, blocking both IDO1 and an immune checkpoint pathway showed more effective control of tumor growth than inhibiting the immune checkpoint alone." (PMID 39534601, 2024). "Interrogation of the tumor immune microenvironment allows capturing dynamic interactions between IDO1 and other immune markers." (PMID 38632994, 2024). "Previous bioinformatic analyses have examined the IDO1–glycolysis link in tumor tissues, yet they fell short of concretely defining the role of cancer cell‐expressed IDO1 in glycolysis." (PMID 38706741, 2024). "In case 10 IDO1 expression was only seen on a small number of tumour epithelial cells at the tumour margin and in case 11 IDO1 expression was only observed on tumour cells in TMA cores taken from peri-neural and lymphocytic rich regions." (PMID 38762572, 2024). "Compared with free EPA, EPA nanovesicles maintain higher stability in the circulatory system, accumulate and release at tumor sites through clathrin-mediated endocytosis, and enhance IDO1 inhibition and T cell proliferation." (PMID 39766335, 2024). "The indoleamine 2,3-dioxygenase 1 (IDO1) inhibitor 4PI can suppress the IDO1-mediated production of kynurenine (Kyn) upon tumor accumulation, while CaCO3 neutralizes tumor acidity by reacting with protons within the TME." (PMID 39045421, 2024). "IFNγ expression can also lead to tumor-repopulating cells entering dormancy through upregulation of IDO1/aryl hydrocarbon receptor (AhR) dependent-p27 induction but prevents apoptosis." (PMID 38216787, 2024).
tumor (continued). "Investigating IDO1 expression against clinicopathological characteristics of HNSCC patients using the UACLAN database revealed a significant decrease in IDO1 expression with increasing tumor stage." (PMID 38736462, 2024). "In different cell populations, including tumor cells and histiocytic cells, IDO1 is also contained in endosomes and can be secreted in extracellular vesicles." (PMID 39061522, 2024). "The effects of hypoxia on IDO1 are potentially cell-type specific as expression of IDO1 in tumour cells (i.e. OC cells) is reduced under hypoxic conditions." (PMID 38352889, 2024). "On the other hand, mast cells in metastatic lymph nodes express lower levels (p < 0.001) of IDO1 than the mast cells in the primary tumor." (PMID 38736462, 2024). "Epacadostat and other IDO-1 inhibitors, including indoximod and navoximod, are also in clinical development for other tumor types." (PMID 39054430, 2024). "These inhibitors inhibit tumor progression by blocking the activity of IDO1 and TDO through different mechanisms." (PMID 38462620, 2024). "Generally, IDO-1 expression is known to be up-regulated in cancer and serves as an immunosuppressive and immune evasive mechanism by tumor cells." (PMID 39376560, 2024). "First, leveraging the material’s properties, 4PI is released under tumor acidic conditions to inhibit IDO1-mediated Kyn production, thereby reversing acidosis-induced radioresistance and suppressing the generation of immunosuppressive Kyn." (PMID 39045421, 2024). "In the current study, we demonstrated that, in SKOV-3 tumor cells, epacadostat increases and persistently stabilizes IDO1 protein in a catalytically inactive conformation, interestingly maintained even after the epacadostat washout." (PMID 38333210, 2024). "We validated the expression of IDO1 in the stroma and parenchyma of tumour samples from our clinical center in a computer-guided digital manner with QuPath software." (PMID 39351094, 2024). "IDO-1 expression was observed on tumour cells in 7/12 cases but would only have been detected in 3/12 cases if the TMA had only contained tumour rich cores." (PMID 38762572, 2024). "Indoleamine 2,3-dioxygenase 1 (IDO1) is an intracellular immune checkpoint highly expressed by both tumor and immune cells in the TME, where it mediates the ‘off’ signal that blocks T cells from killing cancer cells." (PMID 38333210, 2024). "IDO1 inhibitors have been used in clinical trials for cancer immunotherapy and have emerged as a critical target for tumor immunotherapy." (PMID 38558328, 2024). "Tumoral IDO1 expression, however, not only inhibits anti-cancer immune defenses but also facilitates the survival, motility, and chemoresistance of tumor cells, as well as neo-angiogenesis and metastasis." (PMID 39061522, 2024). "The intracellular enzyme IDO-1 is expressed in dendritic cells, macrophages, and endothelial cells in the tumour microenvironment." (PMID 38188364, 2024). "Focal expression of IDO-1 on tumour epithelial cells was seen in 7/12 patients but would only have been 3/12 cases if only tumour rich cores had been sampled." (PMID 38762572, 2024). "Tumors can also upregulate key catabolic enzymes like ARG1 or indoleamine 2,3-dioxygenase 1 (IDO1) in myeloid cells to deplete arginine and tryptophan within a tumor, which are crucial for regulating T-cell differentiation and proliferation." (PMID 38216787, 2024). "The IDO1 expression in these tumor cells (TC1, TC2, TC4, TC6, TC7, TC9) and the concentration of IDO1 in TCMs were examined." (PMID 38540186, 2024). "To define in better detail the cellular compartment expressing IDO1 we co-stained Vil Apc Dock2 tumour tissue for epithelial and immune cell markers alongside IDO1." (PMID 39242821, 2024). "In this work, a certain number of highly expressed IDO1 tumor cells were identified and named IDO1_fib." (PMID 38443340, 2024).
tumor (continued). "There was a statistically significant correlation between a higher percentage of IDO1-positive tumor cells and the following parameters, i.e., a lower mitotic count and a rise in IRS and H-scores for ER-α or PR, respectively." (PMID 39061522, 2024). "It is worth noting that IDO1, IDO2, CD44, and CD200 are up-regulated in the FRM high-risk group, all of which are related to the tumor microenvironment." (PMID 38534739, 2024). "For the regulatory axis IDO1/miR-18a/NKG2D/NKG2DL in the tumor microenvironment, cytotoxicity of NK cells regulated with high expression of IDO1 was significantly reduced, regulating NK cell function." (PMID 38539263, 2024). "IDO1 is frequently activated in various types of human cancers, including BC, and affects the innate immune system, tumor, and stromal cells." (PMID 39371092, 2024). "IDO inhibitors as monotherapy have generally shown limited efficacy in tumor treatment, and research has indicated a complex interplay between IDO1 expression, PD‐1 expression, and immune therapy resistance." (PMID 39492834, 2024). "In summary, the high expression of FSTL3 can lead to anti-PD1 therapy resistance, and the combination with IDO1 inhibitor can sensitize the therapy for a better anti-tumor effect." (PMID 38302412, 2024). "Of potential clinical importance, elevated expression of ISG15 in the TME has been linked to higher histological grade, larger tumor size, a “stemmy” cancer phenotype, low CD8+ TIL content, expression of PD-L1/IDO-1/LAG-3, and poor clinical prognosis." (PMID 38312842, 2024). "Our in vivo differential gene expression analysis revealed a downregulation of the gene IDO1 which codes for a tumor-promoting enzyme and the gene for the metastasis-promoting cytokine IL6 was also downregulated." (PMID 39335552, 2024). "Other in vivo studies have shown that IDO1 expression contributes to tumor angiogenesis in ovarian cancer and lung adenocarcinomas." (PMID 39065567, 2024). "In this example, a considerable increase in circulation time of the IDO1 inhibitor-micelle over doxorubicin was observed, as well as significantly prolonged survival and tumor reduction over both doxorubicin and liposomal doxorubicin." (PMID 39030582, 2024). "We also conducted a comparison analysis of IDO1 expression levels in different cells between the primary tumor and metastatic lymph nodes." (PMID 38736462, 2024). "Then, we established a xenograft tumor model using control and IDO-1 knockdown MDA-MB-231 cells, followed by treatment via adoptive transfer of NK cells and/or injection with the HLA-G antibody." (PMID 37981615, 2024). "In this study, we found that IDO-1, upon induction by tumor environmental cytokines like IFN-γ, can suppress the tumoricidal capacity of NK cells by up-regulating HLA-G." (PMID 37981615, 2024). "This analysis revealed that cancer cells in metastatic lymph nodes express higher levels of IDO1 than cancer cells in the primary tumor." (PMID 38736462, 2024). "The majority of tumors (n = 91; 95%) contained calponin-positive tumor cells ranging from 2 to 22 percent (median: 8%), these tumors also included the six IDO1 immunonegative tumors." (PMID 39061522, 2024). "This regulatory cascade ultimately leads to augmented IDO1 expression, resulting in heightened synthesis of kynurenine (Kyn) in tumor cells." (PMID 38816360, 2024). "Macro-IDO1 was predominantly enriched in preca-OLK and OSCC, distributed near exhausted T cells and possessed tumor associated macrophage transformation potentials." (PMID 39239507, 2024). "In HCC, tumour cells can promote the expression of pro‐proliferative genes and inhibit cell cycle inhibitory molecules to promote proliferative capacity via the IDO1‐AHR‐β‐catenin pathway." (PMID 38935536, 2024). "Diffuse IDO1 expression within the entire cytoplasm of tumor cells was observed in tumor areas with all growth patterns, i.e., solid, tubular, papillary, and cystic, and was either granular or nongranular." (PMID 39061522, 2024).